FOXM1 (forkhead box M1)
Diseases named in the same sentence as FOXM1 in open-access papers (continued):
Sharing a sentence is not in itself a finding about the gene and the disease.
cancer (continued). "Many studies have linked the transcription factor FOXM1 to a broad range of different human cancers, including OAC." (PMID 25889361, 2015). "PLK1 inhibitors are currently being developed for cancer therapy and it is likely that cells demonstrating coordinated up regulation of FOXM1 and PLK1 expression will be particularly susceptible to such treatment." (PMID 26576650, 2015). "Loss of function experiments demonstrates the importance of FOXM1 for their expression whereas co-expression across OAC cancer samples is suggestive of a role for FOXM1 in driving the expression of a large proportion of its target gene network." (PMID 25889361, 2015). "Several lines of evidence have demonstrated that FOXM1 is associated with tumor initiation, promotion, invasion, and metastasis, suggesting that FOXM1 contributes to all major hallmarks of cancer." (PMID 24918286, 2014). "Increased expression of FOXM1 was associated with an expansion of the cancer stem-like cell population and with increased cell invasiveness and resistance to endocrine treatments." (PMID 25213081, 2014). "The forkhead factor FOXM1 was first linked with cancer in 2002 and has subsequently been shown to be involved in cancer initiation, progression and prognosis in diverse tissue types." (PMID 23347430, 2013). "FOXM1 is an example of FOTS core genes involved in both of epithelial cancer cells and the cancer associated fibroblasts." (PMID 24342436, 2013). "FOXM1 is a proliferation associated transcription factor which has increasingly been found to play a role in the pathogenesis of a wide range of human cancers." (PMID 23365673, 2013). "FoxM1 overexpression has also been reported to be associated with worse prognosis and to serve as a prognostic marker in numerous types of human cancers." (PMID 23006512, 2012). "Emerging evidence has reported that aberrant upregulation and activation of GRB7, ERK as well as FOXM1 are closely associated with aggresivenesss of human cancers." (PMID 23285101, 2012). "Previous studies have shown that constitutive activation of ERK activity or increased expression of GRB7 and FOXM1 are closely associated with tumorigenicity of various human cancers." (PMID 23285101, 2012). "Taken together, these studies support a driver role of FOXM1 in cancer predisposition and initiation through perturbation of the genomic and epigenomic landscapes." (PMID 23087907, 2012). "Given that FOXM1 has been implicated in all stages from cancer initiation, progression, metastasis to drug resistance, FOXM1 is evidently a promising cancer biomarker." (PMID 23087907, 2012). "FOXM1 expression level has been shown in numerous types of human cancer to be dose-dependently correlated with tumor progression starting from cancer predisposition and initiation, early premalignancy and progression to metastatic invasion." (PMID 23087907, 2012). "Numerous studies have documented that FOXM1 has multiple functions in tumorigenesis and its elevated levels are frequently associated with cancer progression." (PMID 21858223, 2011). "This implicates a possible association between FOXM1 upregulation and enhanced proliferation and invasiveness of cancer cells." (PMID 18254960, 2008). "Indeed, FOXM1 is repeatedly identified as a common factor associated with the higher cancer stage and weaker response to cancer therapies by regulating several targets relevant to drug response and cell survival." (PMID 41714589, 2026). "FOXM1 is a pivotal transcription factor that modulates proliferation-associated genes through complex protein-DNA and protein-protein interactions, making it a highly attractive target in cancer therapy." (PMID 42070099, 2026). "FOXM1 was reported to be associated with poor prognosis in multiple cancers, including LUAD." (PMID 40018029, 2025). "FOXM1 is known to be cell cycle‐dependent, with its overexpression linked to various cancers." (PMID 40091487, 2025).
cancer (continued). "Clinically, DNMT1 expression was inversely correlated with miR-34a-5p expression, whereas a positive correlation was noted between DNMT1 and FoxM1 expression levels, and high DNMT1 levels, low miR-34a-5p levels, and high FoxM1 levels were associated with cancer recurrence." (PMID 40050970, 2025). "In addition to OC, cancer cell stemness has been associated with FOXM1 in other cancers, including breast, colon, prostate, lung, and endometrial cancers." (PMID 40612352, 2025). "Increased FOXM1 expression is closely linked with advanced tumor staging, a high proliferation rate, and an unfavorable prognosis, highlighting its potential as a novel prognostic marker for cancer patients." (PMID 40959276, 2025). "For example, studies have shown that high FOXM1 expression is associated with poor prognosis in a variety of cancers, suggesting that FOXD family genes may follow a similar mechanism in CRC." (PMID 39494294, 2024). "However, chemoresistance associated with high FOXM1 levels in cancer cells decreased the efficacy of these therapies against cancer cells." (PMID 38697979, 2024). "Furthermore, the activation of FOXM1 has been associated with the development of cancers through the c-Myc oncogene." (PMID 38886738, 2024). "Forkhead box M1 (FoxM1) is implicated in cancer progression and chemoresistance." (PMID 36860922, 2023). "Moreover, the knockdown of FOXM1 in the human cancer cell can be susceptible to apoptosis, including PDAC cells." (PMID 36829815, 2023). "Moreover, high expression of HMGA1 and FOXM1 was associated with a poor prognosis in the overall cancers." (PMID 37240870, 2023). "FOXM1 contributes to the occurrence and progression of various types of human malignancies, and it is significantly associated with the poor clinical prognosis of patients with cancer." (PMID 37288663, 2023). "A meta-analysis conducted by Li and colleagues analyzed 23 publications, including nearly 3000 patients across 14 different cancer types, and found that FOXM1 overexpression was associated with reduced overall survival at 3, 5, and 10 years and a more advanced TMN stage." (PMID 37174744, 2023). "Thus, it has been indicated that FOXM1 can be treated as a latent therapeutic target of cancer, which caused more and more attention." (PMID 37159818, 2023). "Interestingly, CD276 was positively associated with FOXM1 expression in most cancers, with the exception of CESC, CHOL, COAD, GBM, READ, SARC and UCS." (PMID 36435510, 2022). "The FOXM1 is required for normal cellular proliferation; however, overexpression of this gene has been implicated as a major predictor of adverse outcomes in 18,000 cancer cases across 39 human malignancies." (PMID 35378133, 2022). "There was a positive association of FOXM1 expression with macrophage M1 in 9 types of cancers." (PMID 36435510, 2022). "It has been found that FOXM1 plays a vital role in mitosis, and its abnormal expression can cause spindle defects, which can delay mitosis and ultimately participate in the development of cervical, liver, lung and other cancers." (PMID 35392402, 2022).
cancer (continued). "CMap is a multifunctional online tool that enables users to compare gene expression signatures that arise from genetic perturbations in cancer cells (e.g., loss of FOXM1) to a large library of gene signatures that reflect the impact of small-drug inhibitors on cancer cells." (PMID 35794249, 2022). "As elevated reactive oxygen species (ROS) levels are implicated in the promotion of cancer cell growth and the metastatic progression, we examined whether ROS was critical for the expression of FOXM1." (PMID 35656815, 2022). "Furthermore, mutated NPM1 is closely associated with FOXM1 inactivation, which is a protein involved in cancer development and chemoresistance." (PMID 35884517, 2022). "Interestingly, overexpression of FOXM1 is a common feature of most human cancers, and it is associated with disease progression and adverse prognosis in multiple human cancer types." (PMID 33805928, 2021). "Several studies have shown that FOXM1 activation is closely associated with cancer progression." (PMID 34073071, 2021). "Consistently, we found that FOXM1 was overexpressed in the tumor tissues of many different cancer types, and the expression dynamics of the eigengene module containing FOXM1 was positively associated with the increase in the proportion of follicular helper T cells and M0 macrophages." (PMID 34489925, 2021). "FOXM1 was recently reported to induce DNA replication pressure in vitro, and FOXM1 expression was observed to be associated with the expression of DNA replication pressure biomarkers in several cancer types." (PMID 35173608, 2021). "Moreover, FOXM1 binds to known FOXM1 targets in cancer cells: the CCNB1 and PLK1 gene promoters (CCNB1 encodes CYCLINB1 and PLK1 encodes Polo kinase 1, respectively) in WG4 cells as demonstrated by ChIP-qPCR." (PMID 34131149, 2021). "Moreover, the overexpression of FOXM1 enhances chemoresistance in various cancers, whereas the deficiency of FOXM1 suppresses cancer cell proliferation, growth, progression, and oncogenesis." (PMID 34073071, 2021). "In addition, FOXM1 is frequently expressed in various cancers, and its expression is associated with cancer aggressiveness." (PMID 34117362, 2021). "Interestingly, SETD3 regulates the expression of other genes associated with cancer such as β-actin, FOXM1, FBXW7, Fascin, eNOS, and MMP-2." (PMID 32042016, 2020). "FOXM1, a major hallmark of cancer was significantly downregulated in GSC and NSCC." (PMID 32164385, 2020). "Moreover, FOXM1 plays an important role in the early stage of metastasis, by stimulating the expression of genes associated with the invasion and migration of cancer cells." (PMID 33053721, 2020). "Several studies suggest FOXM1 overexpression confers acquired tolerance to chemotherapy through the regulation of numerous genes, including ATP-binding cassette genes, DNA damage repair genes, apoptosis-associated genes, cancer stem cell-related genes." (PMID 33292277, 2020). "MELK, as a member of kinases family which is directly regulated by the FOXM1 transcription factor, has been proven to function as an oncogenic gene that is closely associated with mitotic progression as well as the proliferation in multiple human cancers." (PMID 33061942, 2020). "However, the molecular mechanisms underlying the FOXM1 regulation in cancer cells particularly in GSCs were poorly understood." (PMID 33124191, 2020). "Additionally, through the TCGA database, it revealed that FoxM1 is overexpressed in most cancer types, and the expression level is also associated with disease prognosis." (PMID 32551039, 2020). "FOXM1 is highly expressed in several cancers and has also been implicated in poor prognosis." (PMID 33680951, 2020). "(2014) identified KIF2C as a novel FOXM1 transcriptional target that may be implicated in the acquisition of chemoresistance in cancer treatment." (PMID 31579605, 2019).
cancer (continued). "In addition, higher expression of FOXM1 is associated with poor prognosis of patients with cancer and can serve as an independent predictor of poor survival in cancer." (PMID 30782607, 2019). "Furthermore the FOXO3a–FOXM1 axis has been implicated in cancer related processes like proliferation, survival, drug resistance, angiogenesis, migration, and DNA repair in other cancers." (PMID 31238586, 2019). "Other than serving as a cancer-specific diagnostic marker, FOXM1 is also a key anticancer target." (PMID 31877715, 2019). "Previous studies have shown the association of FoxM1 with VEGF, MMP-9 and MMP-2 in various cancers leading to increased invasiveness and migratory ability of cancer cells causing metastasis, and targeting FoxM1 has been shown to inhibit this phenomena via down-regulation of VEGF, MMP-9 and MMP-2." (PMID 29707121, 2018). "In this study, FOXM1 is closely associated with the stemness of taxane-resistant cancer cells." (PMID 29752436, 2018). "Indeed, overexpression of FOXM1 is common in cancer, and higher expression of FOXM1 is associated with worse survival of patients." (PMID 30360388, 2018). "The proto-oncogene forkhead box M1 (FOXM1) is associated with poor survival in many cancers." (PMID 29959570, 2018). "As it is difficult to detect resident IPF fibroblasts in cancer patients, FoxM1 expression may be a hallmark of abnormal fibroblast phenotype and serve as a prognostic marker indicative of a higher risk of RILF." (PMID 29789556, 2018). "However, molecular basis underling the described roles of FoxM1 in cancer progression still needs to be clarified and different mechanisms have been proposed." (PMID 28770020, 2017). "Consequently, FoxM1 is important for cancer stem cells, depletion of FoxM1 leads to a loss of the cancer stem cells." (PMID 28387346, 2017). "Meanwhile, recent studies have revealed that the oncogenic potential of FoxM1 is determined by its capacity to transactivate target genes that are implicated in different phases of cancer development, including cancer survival, invasiveness, EMT process, and angiogenesis." (PMID 29110682, 2017). "Furthermore, activation of FoxM1 signaling is generally associated with cancer cellular proliferation, invasion and metastasis, and FoxM1 is overexpressed in basal/TNBC." (PMID 29312532, 2017). "As expected, FoxM1 over-expression has been implicated in cancer." (PMID 27703839, 2016). "Moreover, the FOXM1 transcription factor which is over-expressed in many human cancers, is implicated in cancer cells invasion and metastasis." (PMID 27034162, 2016). "Interestingly, the blockade of either of these two kinases effectively caused downregulation of forkhead box protein M1 (FOXM1) activity which is known as an oncogenic transcriptional factor in various types of cancer cells." (PMID 26933922, 2016). "Moreover, it has been shown that higher expression of FOXM1 is associated with a poor prognosis in several cancers." (PMID 26640950, 2015). "Furthermore, it has been shown that the loss of FOXM1 expression in cancer cell lines results in mitotic spindle defects, delays in mitosis and the induction of mitotic catastrophe." (PMID 26640950, 2015). "Increased FoxM1 expression has been implicated in many types of cancers, including HNSCC and ESCC." (PMID 25714027, 2015). "Interestingly, the expression of several proteins, such as survivin, aurora kinases, p16(INK4A) and IGF-1, have been found altered in GEP-NENs, and are associated with FOXM1 expression in other cancer entities." (PMID 25797272, 2015). "FOXM1 is frequently overexpressed in cancer and takes part in each hallmark of cancer." (PMID 26258070, 2015).
cancer (continued). "FoxM1 has been implicated in cell cycle control, proliferation, DNA damage signaling, invasion, angiogenesis, metastasis, resistance to cancer drugs, and aggressive tumor behavior and clinical outcomes." (PMID 25426548, 2014). "In addition to its involvement in uncontrolled cell division during early stages of tumorigenesis, elevated levels of FoxM1 have been found associated with progressive stages of increasing malignancy in a variety of cancers." (PMID 23857410, 2013). "The high expression of ARG2, FGFBP1 and FOXM1, are associated with several cancers." (PMID 24481205, 2013). "Indeed, recent evidence has implicated FoxM1 in several other cancer-related processes such as angiogenesis, invasion, and metastasis." (PMID 23006512, 2012). "The oncogene FOXM1 has been implicated in all major types of human cancer." (PMID 22461910, 2012). "Furthermore, recent data have revealed that FoxM1 is often associated with cancer patients or cell lines that exhibit chemotherapeutic resistance." (PMID 23110199, 2012). "Importantly, the increased FOXM1 expression was associated with the tumor progression of human cancers." (PMID 21858223, 2011). "Deregulation of FOXM1 has been linked to a majority of human cancers." (PMID 20187950, 2010). "Indeed, the high expression of FOXM1 in numerous cancer cell lines and a variety of tumors is always associated with tumor initiation, development, invasion, metastases and poor prognosis by directly potentiating the expression of tumor-related genes, such as ERα, TOPO-2α, c-Myc, DLX1 and PDGF-A." (PMID 39060421, 2024). "Thus, we propose that the impairment of these pathways by STL001-mediated FOXM1 suppression may contribute to the increased vulnerability of FOXM1-deficient cancer cells universally to a broad range of chemotherapeutic drugs." (PMID 38697979, 2024). "Similarly, miR-383 inhibition by circSKA3 could facilitate MB development through its target, FOXM1, which is a critical proliferation-associated transcription factor widely overexpressed during the cell cycle in most human cancers." (PMID 37835380, 2023). "Notably, FoxM1 is linked to cancer cell viability, dissemination, death, and immune escape." (PMID 36301031, 2022). "Moreover, FOXM1 target genes can be linked to broader cancer pathways." (PMID 34205406, 2021). "Notably, pan-cancer analysis identified FOXM1 as the top gene associated with poor prognosis." (PMID 30795624, 2019). "Furthermore, FOXM1 expression is regulated post-translationally in response to epirubicin treatment and these post-translational modifications are associated with epirubicin action and resistance in cancer cells." (PMID 29180117, 2018). "The results identify a new molecular link between cell cycle regulators and regulation of differentiation genes (such as GATA3 and FoxA1) that offers insights also into how over-expression of FoxM1 might be playing a causal role in maintaining poorly differentiated state of cancer cells." (PMID 28387346, 2017). "Moreover, overexpression of FOXM1 is a hallmark of many cancers and a sign of poor prognosis." (PMID 28666461, 2017).